MIR5701-2 (microRNA 5701-2)
Synonyms: hsa-mir-5701-2
Gene: MicroRNA gene on chromosome 15 (21,513,959 to 21,514,040, forward strand). Ensembl gene ENSG00000277841.
Homologues: Paralogues in human: MIR5701-1 (100% identical), MIR5701-3 (100% identical).